CERS1 (ceramide synthase 1)
Description:
Ceramide synthase that catalyzes the transfer of the acyl chain from acyl-CoA to a sphingoid base, with high selectivity toward stearoyl-CoA (octadecanoyl-CoA; C18:0-CoA). N-acylates sphinganine and sphingosine bases to form dihydroceramides and ceramides in de novo synthesis and salvage pathways, respectively. Plays a predominant role in skeletal muscle in regulating C18 ceramide and dihydroceramide levels with an impact on whole-body glucose metabolism and insulin sensitivity. Protects from diet-induced obesity by suppressing the uptake of glucose in multiple organs in a FGF21-dependent way (By similarity). Generates C18 ceramides in the brain, playing a critical role in cerebellar development and Purkinje cell function (By similarity). In response to cellular stress mediates mitophagy, a known defense mechanism against cell transformation and aging. Upon mitochondria fission, generates C18 ceramides that anchor lipidated MAP1LC3B/LC3B-II autophagolysosomes to outer mitochondrial membranes to eliminate damaged mitochondria.
Synonyms: LAG1; LASS1; UOG1; EPM8
Tractability: Antibody: UniProt predicts a signal peptide or a membrane-spanning region. PROTAC: ubiquitination databases record sites on it.
Target class: Enzyme; Transferase
Gene: Protein-coding gene on chromosome 19 (18,868,545 to 18,896,727, reverse strand). Ensembl gene ENSG00000223802.
Subcellular location: Endoplasmic reticulum membrane
Subcellular location (Human Protein Atlas): Endoplasmic reticulum
Pathways (Reactome):
Metabolism: Sphingolipid de novo biosynthesis
Gene Ontology:
Molecular function: sphingosine N-acyltransferase activity; acyltransferase activity, transferring groups other than amino-acyl groups
Biological process: cellular response to dithiothreitol; cellular response to mycotoxin; cellular response to UV-A; cellular response to xenobiotic stimulus; ceramide biosynthetic process; positive regulation of mitophagy; sphingolipid biosynthetic process; sphingomyelin biosynthetic process; negative regulation of cardiac muscle hypertrophy; negative regulation of D-glucose import; sphingolipid metabolic process
Cellular component: cytoplasmic side of endoplasmic reticulum membrane; endoplasmic reticulum; endoplasmic reticulum membrane; membrane
Genetic constraint (gnomAD): Loss-of-function variants: 13 observed, 30.16 expected, observed/expected ratio (o/e) 0.43, 90% interval 0.28 to 0.69. The synonymous counts are far from expectation, so gnomAD's model fits this gene poorly and the ratio says little. Missense variants: 411 observed, 383.53 expected, observed/expected ratio (o/e) 1.07, 90% interval 0.99 to 1.16. Synonymous variants: 223 observed, 167.3 expected, observed/expected ratio (o/e) 1.33, 90% interval 1.19 to 1.49.
Gene-disease validity (ClinGen):
ClinGen rates the evidence that CERS1 causes each of these diseases.
progressive myoclonus epilepsy (autosomal recessive): Moderate. A rare group of disorders characterized by the development of myoclonic and tonic-clonic epileptic seizures associated with progressive degeneration of the nervous system.
Homologues: Orthologues: macaque CERS1 (98% identical), dog CERS1 (94% identical), pig CERS1 (92% identical), mouse Cers1 (81% identical), rat Gdf1 (81% identical), chimpanzee CERS1 (68% identical), tropical clawed frog cers1 (61% identical), guinea pig CERS1 (59% identical), zebrafish cers1 (54% identical), Caenorhabditis elegans lagr-1 (32% identical). Paralogues in human: CERS6 (29% identical), CERS4 (28% identical), CERS5 (28% identical), CERS2 (26% identical), CERS3 (23% identical).
Diseases named in the same sentence as CERS1 in open-access papers:
CERS1 is named in the same sentence as 59 diseases in open-access papers, as found by Europe PMC text mining. Sharing a sentence is not in itself a finding about the gene and the disease. The quoted sentences say what the papers report.
head and neck squamous cell carcinoma (13 papers, 2020 to 2025). A squamous cell carcinoma that arises from any of the following anatomic sites: lip and oral cavity, nasal cavity, paranasal sinuses, pharynx, larynx, and salivary glands. "A previous study demonstrated that CERS1 overexpression increased C18-ceramide production in human head and neck squamous cell carcinoma, thereby causing telomerase activity disorder and mitochondrial dysfunction, ultimately leading to cell apoptosis." (PMID 37046655, 2023). "For example, CerS1 and CerS6 which generate C18- and C16-ceramides respectively were shown to have both pro-apoptotic and pro-survival roles in head and neck squamous cell carcinoma (HNSCC)." (PMID 38720356, 2024). "Mitophagy is a significant concept in the CERS1 with head and neck squamous cell carcinomas (HNSCC)." (PMID 37614280, 2023). "CerS1 has been identified to play a role in the pathogenesis of head- and neck squamous cell carcinoma (HNSCC)." (PMID 37760612, 2023). "CerS1 is notable for its synthesis of C18-ceramide, a pro-apoptotic and anti-tumorigenic ceramide that has been shown to be downregulated in head and neck squamous cell carcinoma (HNSCC) compared to healthy control tissue." (PMID 34069611, 2021). "It has been reported in head and neck squamous cell carcinoma that CerS1/C18-ceramide binds to LC3B-II protein, which binds ceramide to the outer mitochondrial membrane (OMM)." (PMID 32121501, 2020). "For example, C18-ceramide synthesized by ceramide synthase 1 (CERS1) induces mitophagy and tumor suppression in head and neck squamous cell carcinoma cells and acute myeloid leukemia cells in vitro and in vivo." (PMID 33262988, 2020). "Similarly, histone deacetylase 1 (HDAC1) and microRNA-574-5p axis was found to repress CerS1 and alter C18 ceramide generation in head and neck squamous cell carcinoma (HNSCC), thereby allowing tumor growth and proliferation." (PMID 35565311, 2022). "C18-ceramide generation by CERS1 expression in multiple head and neck squamous cell carcinoma (HNSCC) cell lines, or their treatment with the mitochondria-accumulating ceramide analog D-e-14C18-pyridinium ceramide bromide, selectively induced lethal mitophagy independently of apoptosis." (PMID 35011599, 2021). "Besides, CerS1/C18-ceramide can induce tumor suppression in model of head and neck squamous cell carcinoma (UM-SCC-22A) xenograft tumor formation." (PMID 32121501, 2020). "For example, in head and neck squamous cell carcinoma (HNSCC), while ceramide synthase 1–generated C18-ceramide inhibits its tumor growth, ceramide synthase 6–mediated C16-ceramide induces its tumor growth." (PMID 38599378, 2024). "For example, CerS1 generates C18-ceramide, mediating cell death and tumor suppression in acute myeloid leukemia (AML) and head and neck squamous cell carcinoma (HNSCC), while CerS6 has an antiapoptotic role in ER stress responses and produces mainly C16-ceramide." (PMID 32121501, 2020).
Insulin resistance (13 papers, 2013 to 2024). Increased resistance towards insulin, that is, diminished effectiveness of insulin in reducing blood glucose levels. "The enzyme ceramide synthase 1 (specifically involved in the biosynthesis of Cer(d18:0/18:0),) is inversely associated with alterations in murine models of insulin resistance." (PMID 27044508, 2016). "Ceramide synthase 1 (CerS 1) is reported to be specific for the synthesis of dhCer 18∶0/Cer 18∶0 and its expression in muscle has been shown to be inversely associated with alterations in glucose tolerance in a mouse model of insulin resistance." (PMID 24086336, 2013). "Specifically, C18 ceramide, synthesized by ceramide synthase 1 (CerS1), is abundant in skeletal muscle and is suggested to promote insulin resistance in humans." (PMID 38892556, 2024). "The knockout of CerS1 in the skeletal muscle of C57BL/6 mice was reported to prevent C18-ceramide accumulation with improvements in insulin resistance and glucose tolerance." (PMID 36077094, 2022). "To achieve this goal, we investigated the effect of local in vivo shRNA-mediated gene silencing of CerS1 and CerS5 on the bioactive lipid accumulation and insulin signaling pathway in gastrocnemius muscle of mice with diet-induced insulin resistance." (PMID 35053322, 2022). "C18 ceramide, produced mainly by CerS1, also accumulated in mice fed with a high-fat diet that promotes systemic insulin resistance." (PMID 36548725, 2022). "C18 ceramide, synthesized by ceramide synthase 1 (CerS1), is abundant in skeletal muscle and suggested to promote insulin resistance in humans." (PMID 30131496, 2018). "This provides a potential mechanism where cellular stress, like nutrient overload, may induce transfer of CerS1 to mitochondria, increasing mitochondrial ceramide to trigger insulin resistance." (PMID 38149844, 2023). "Our results indicate that C18:0-Cer is a key ceramide species involved in the induction of skeletal muscle insulin resistance, and the CerS1 could be potential important target for insulin resistance pharmacotherapy." (PMID 35053322, 2022). "Therefore, inhibition of CerS6, and perhaps CerS1 and CerS5, may serve as an attractive therapeutic approach for treating insulin resistance, obesity, fatty liver, and NASH." (PMID 32849276, 2020). "One previous study has demonstrated that the level of C18:0 ceramide production in skeletal muscle was reduced in mice lacking CerS1, which effectively prevented obesity-induced insulin resistance." (PMID 36594091, 2023). "However, the results do not overlap with another group of researchers who have shown that the use of a CerS1-specific inhibitor increases the rate of fatty acid oxidation in muscle, but does not protect against diet-induced insulin resistance." (PMID 35053322, 2022). "Our results support a model in which CerS1 activity and C18 ceramide in SkM are not requisite for the development of insulin resistance in mice fed a HFD, but do play a very significant role in storage of dietary fats by acting as a brake on mitochondrial fatty acid oxidation." (PMID 30131496, 2018).
Obesity (8 papers, 2018 to 2023). Accumulation of substantial excess body fat. "Still, it is predicted that CerS1-derived C18:0 ceramides cause metabolic deterioration in obesity and that CerS1 inhibition provides a promising strategy for treating obesity-related metabolic abnormalities." (PMID 35789435, 2022). "In addition to our observation that CerS6-derived C16:0 ceramides promote metabolic deterioration in obesity, we have previously identified a role of skeletal muscle CerS1 and its product C18:0 ceramide in the development of obesity-associated insulin resistance." (PMID 38016943, 2023). "Knockout experiments in mice have further confirmed the exceptionally critical role of CerS1-derived C18:0 ceramides in skeletal muscle in obesity." (PMID 35789435, 2022). "Endogenous ceramide production in skeletal muscle is increased in mouse models of diet-induced obesity, which show increased CerS1 expression and elevated muscle C18:0 ceramide content." (PMID 35789435, 2022). "In contrast to what we observed in mice with CerS6 deficiency in Nkx2.1-expressing cells, inhibiting CerS1 in neurons of the hypothalamus did not affect HFD-induced obesity, systemic insulin sensitivity, or glucose tolerance." (PMID 38016943, 2023). "Hence, these data indicate that CerS1-derived C18:0 ceramides in neurons of the hypothalamus do not promote the obesity-associated deterioration of glucose homeostasis, as opposed to their critical role in skeletal muscle and that of hypothalamic CerS6." (PMID 38016943, 2023). "Surprisingly, deleting CerS1 in skeletal muscle to reduce C18:0 ceramide synthesis in obesity did not appreciably affect muscle-specific insulin signaling or glucose uptake." (PMID 35789435, 2022).
cerebellar ataxia (6 papers, 2011 to 2022). A neurological syndrome characterized by clumsy and uncoordinated movement of the limbs, trunk, and cranial muscles. "Spontaneous recessive mutations of the CerS1 gene cause ataxia, linked to a loss of Purkinje cells in the murine brain." (PMID 31692231, 2020). "With regard to CerS1 deficient mice, a well‐described cerebellar defect manifesting in ataxia may have co‐founding effects on the development of muscular atrophy as observed in CerS1Δ/Δ mice." (PMID 31692231, 2020). "Moreover, a deficiency of ceramide biosynthesis caused by mutations in the Lass1 gene encoding ceramide synthase 1 (CerS1) has been shown to cause cerebellar ataxia and Purkinje cell degeneration." (PMID 25908616, 2015). "Lost activity of CerS1 has been reported to trigger early-onset cerebellar ataxia and cerebellar Purkinje cell degeneration in mice." (PMID 29311779, 2017). "With respect to CerS1, the cerebellar damage detected in CerS1Δ/Δ mice shows all signs of ataxia with severe movement disorders, which could have an indirect yet co‐founding effect on muscle homeostasis." (PMID 31692231, 2020). "In addition to the marked hepatopathy, the lack of CerS1 and CerS2 is linked with cerebellar ataxia and multiple structural changes in the peripheral and central nervous systems, respectively." (PMID 36139213, 2022).
glioma (6 papers, 2017 to 2023). A benign or malignant brain and spinal cord tumor that arises from glial cells (astrocytes, oligodendrocytes, ependymal cells). "In this study, CHOP RNAi blocking ER stress, 3-MA inhibiting autophagy and IGF-1 activating PI3K/AKT pathway could recover depression of cell viability caused by CERS1 overexpressed in glioma cells." (PMID 29262618, 2017). "In human glioma tissue, C18-ceramide levels are lower than in control tissue, and overexpression of CerS1 or exogenous C18-ceramide triggers ER stress, lethal autophagy, and cell death in glioma cell lines." (PMID 37760612, 2023). "The induced overexpression of CerS1 in the IDHwt U251 and A172 glioma cells results in increased C18 ceramide levels and induces autophagy." (PMID 36012521, 2022). "One recent study reported that the overexpression of CerS1 increased C18-Cer level and led to lethal autophagy in human glioma cells." (PMID 32626514, 2020). "To determine the functions of C18-ceramide in glioma, we increased the expression of CERS1 and CERS1 (H138A) by pcDNA3.1(+)/CERS1 transfection, which exclusively synthesized C18-ceramide, in glioma cells U251 and A172." (PMID 29262618, 2017). "The elevation of p-PERK and p-eIF2α also indicated CERS1-induced ER stress in U251 and A172 glioma cells." (PMID 29262618, 2017). "We also verified these results using qRT-PCR analysis; the mRNA levels of ATF-4, XBP-1 (s), and CHOP obviously increased in U251 and A172 glioma cells in which CERS1 was overexpressed." (PMID 29262618, 2017). "Overexpression of CERS1 or adding exogenous of C18-ceramide inhibited cell viability and promoted cell death in glioma cells, accompanied by the activation of ER stress, induction of lethal autophagy, and inhibition of the PI3K/AKT signaling pathway." (PMID 29262618, 2017). "In our study, overexpression of CERS1 or adding exogenous of C18-ceramide promoted sensitivity of glioma cells to VM-26." (PMID 29262618, 2017). "By Western blot, the protein levels of ATF-4, XBP-1 (s), and CHOP increased in U251 and A172 glioma cells in which CERS1 was overexpressed." (PMID 29262618, 2017). "Overexpression of CERS1 or adding exogenous of C18-ceramide reduced glioma cell viability, at least partially by enhancing cell death." (PMID 29262618, 2017). "Conversely, the mRNA level of CERS6 was significantly decreased in CERS1 overexpressed glioma cells." (PMID 29262618, 2017). "Taken together, overexpression of CERS1 or adding exogenous of C18-ceramide increased the sensitivity of U251 and A172 glioma cells to VM-26." (PMID 29262618, 2017). "Here, we further reported that CERS1/C18-ceramide in combination with teniposide (VM-26) displayed an even greater inhibitory effect on the U251 and A172 glioma cells than did VM-26 alone." (PMID 29262618, 2017). "As a result, the conversion of LC3B-I (upper band) to LC3B-II (lower band) and reduction of p62 reflected the occurrence of autophagy in U251 and A172 glioma cells in which CERS1 was overexpressed." (PMID 29262618, 2017). "These roles were examined by reconstitution of C18-ceramide in U251 and A172 glioma cells via addition of exogenous C18-ceramide or overexpression of CERS1, which has been shown to specifically induce the generation of C18-ceramide." (PMID 29262618, 2017). "This may have important implications for the sphingolipid rheostat, given that the pro-apoptotic C18 ceramide produced by Cers1 and CerS4 is preferentially sequestered to lipid droplets in certain gliomas." (PMID 36012521, 2022). "On the other hand, a 70% reduction of C18-ceramide content was reported in GBM compared to normal brain tissue, while overexpressed CerS1 or exogenously added C18-ceramides showed inhibition of cell viability and induced apoptosis in cultured human glioma cells." (PMID 34445547, 2021). "Interestingly, combined with the overexpression of CERS1 in glioma cells, the mRNA level of CERS4 was also increased." (PMID 29262618, 2017).
glioma (continued). "In our study, overexpression of CERS1 also inhibited glioma cell viability and induced cell death." (PMID 29262618, 2017). "Thus, CERS1 and C18-ceramide potentially delayed the growth of gliomas cells and inhibited the DNA synthesis." (PMID 29262618, 2017). "In conclusion, overexpression of CERS1 in glioma cells induced activation of ER stress." (PMID 29262618, 2017). "Furthermore, CERS1 or C18-ceramide combined with VM-26 had better efficacy in cell viability inhibition and cell death induction of human glioma cells than did VM-26 alone." (PMID 29262618, 2017). "Moreover, overexpression of CERS1 or adding exogenous C18-ceramide increased the sensitivity of U251 and A172 glioma cells to teniposide (VM-26)." (PMID 29262618, 2017). "We next examined the potential signaling pathways that might induce the cell viability reduction and cell death via overexpression of CERS1 or addition of exogenous of C18-ceramide in glioma cells." (PMID 29262618, 2017). "Thus, the combined therapy of CERS1/C18-ceramide and VM-26 may be a novel therapeutic strategy for the treatment of human glioma." (PMID 29262618, 2017). "However, the roles of CERS1 and C18-ceramide in glioma are largely unknown." (PMID 29262618, 2017). "In our study, the lethal autophagy induced by overexpression of CERS1 was also independent of Bax and Bcl-2 in glioma cells." (PMID 29262618, 2017). "Overexpression of CERS1 or adding exogenous C18-ceramide inhibited cell viability and induced cell death by activating endoplasmic reticulum stress, which induced lethal autophagy and inhibited PI3K/AKT signal pathway in U251 and A172 glioma cells." (PMID 29262618, 2017). "Further data showed that increased generation of C18-ceramide via overexpression of CERS1 or adding exogenous of C18-ceramide resulted in the inhibition of cell viability, which involved the activation of ER stress, induction of autophagy, and modulation of the PI3K/AKT pathway in glioma cells." (PMID 29262618, 2017).
acute myeloid leukemia (3 papers, 2020 to 2021). Acute myeloid leukemia (AML) is a group of neoplasms arising from precursor cells committed to the myeloid cell-line differentiation. "The tumor-suppressive role of ceramide-induced mitophagy is also evident from the study in acute myeloid leukemia (AML), where FLT3-ITD (mutant Fms-like tyrosine kinase 3–internal tandem duplication) signaling downregulated the CerS1/C18-ceramide which confers its resistance to cell death." (PMID 35011599, 2021).
colorectal cancer (3 papers, 2022 to 2025). A primary or metastatic malignant neoplasm that affects the colon or rectum. "To investigate the role of CERS1-6 in colorectal cancer, we examined the mRNA expression levels of CERS1-6 in colorectal cancer tissue and paired normal colorectal mucosal tissue." (PMID 37758931, 2023). "verified that CERS1 was highly expressed in colorectal cancer by PCR." (PMID 40963858, 2025).